RHOA (ras homolog family member A)
Diseases named in the same sentence as RHOA in open-access papers (continued):
Sharing a sentence is not in itself a finding about the gene and the disease.
cancer (continued). "LARG contributes to the development and progression of several diseases, especially cancer, through its ability to activate RhoA." (PMID 41338458, 2025). "Experimental findings further demonstrated that macrophages facilitate cytoskeletal rearrangement by activating the Ras homolog family member A (RhoA) signaling pathway, thereby enhancing cancer cell migration." (PMID 40565016, 2025). "Among them, SDF-1α incubation stimulates CXCR4, which in turn activates the RhoA/ROCK-mediated cascade in cancer cells." (PMID 40655948, 2025). "Various studies demonstrated that RhoA/ROCK signaling is essential for cancer metastasis, particularly during EMT process." (PMID 40388100, 2025). "Through binding to cell surface integrin αvβ3 via an RGD motif, the autocrine pro-legumain activates FAK-Src-Ras homolog family member A (RhoA) signaling in cancer cells." (PMID 41294885, 2025). "Using molecular docking, functional experiments, and high-resolution imaging, we showed that SC disrupts RhoA-driven metastatic pathways, providing a mechanistic foundation for its therapeutic potential in advanced cancers." (PMID 40746849, 2025). "It is easy to discriminate the RhoA expression between the non‐cancer control and stage II cancer samples." (PMID 39887960, 2025). "Overexpression of ROCK1 and RhoA correlates with cancer progression and plays a pivotal role in determining cancer cell motility and invasion phenotype." (PMID 39354653, 2025). "The GEF-H1/RhoA/ROCK pathway has previously been demonstrated to be activated by TTFields in cancer cells and functions as an upstream regulator of NF-κB in myeloid cells." (PMID 41465516, 2025). "The proteomics study confirmed the enrichment of molecules in fibronectin and the VEGF pathway in PAK4KO cancer cells, along with the upregulation of EphA2, RhoA, ROCK1, ROCK2, and components of the EPH-ephrin signalling pathway, linking to enhanced VM." (PMID 41294859, 2025). "This research focuses on two crucial players: RhoA and Rac1, small yet powerful proteins that regulate the structure and movement of cancer cells." (PMID 39887960, 2025). "This consistent upregulation of both RhoA and Rac1 in more advanced tumors points to their potential as key biomarkers for cancer progression." (PMID 39887960, 2025). "We confirm that RhoA is overexpressed in the clinical cancer samples compared to non‐cancer control samples." (PMID 39887960, 2025). "Overexpression of FPR2 in EOC cells enhances RhoA expression, leading to increased migratory capacity of the cancer cells." (PMID 40330466, 2025). "As expected, the relative expression of RhoA was much higher in stage IV cancer samples, followed by stage III, and II respectively." (PMID 39887960, 2025). "Activated FAK and RhoA are also known to promote cell migration, invasion, apoptosis suppression, and angiogenesis in various cancers." (PMID 41440001, 2025). "The analysis revealed that a significant proportion of the cells expressed either RhoA, Rac1, or both, indicating the presence of these proteins across most of the cancer cell population." (PMID 39887960, 2025). "The interaction between ADM and macrophages activates the RhoA signaling pathway in cancer cells, which leads to cytoskeletal rearrangements necessary for cell migration." (PMID 40330466, 2025). "KLK14-dependent activation of PAR-2, NF-kB, and RhoA signaling suggests a complex interplay between protease signaling, inflammation, and cytoskeletal dynamics in HPV-associated cancers." (PMID 40753921, 2025). "Since cell migration is critical for metastasis, GMIP's regulation of RhoA is particularly important for cancer cell migration." (PMID 40275529, 2025). "Upregulation of the RhoA signaling pathway, which plays an important role in oncogenic transformation, was noticed in the cancer group." (PMID 40136660, 2025).
cancer (continued). "ARHGEF10L, belonging to guanine nucleotide exchange factor family, is available to induce GDP/GTP exchange on RhoA,33 and increase in RhoA/Rho kinase signal conduction to promote cancer development and metastasis." (PMID 38180276, 2024). "One signaling pathway that has been shown to be central to cancer development is the RhoA/ROCK signaling pathway because its downstream signaling can control cell cycle progression, survival, cellular senescence, and migration." (PMID 38921484, 2024). "The present study not only enriches the researches of chemerin in female malignant tumor development especially for omental metastasis but also reveals a novel mechanism of CMKLR1/RhoA/ROCK1-mediated EMT in invasion of metastasis of OC cells." (PMID 39104601, 2024). "This phosphorylation event facilitated cancer cell proliferation and motility by activating RhoA and Rac1." (PMID 39768163, 2024). "Increased expression of STRN was found in different cancers, which induced cell cycle progression and invasiveness by activating downstream transcription factors, including misshapen-like kinase 1, RhoA, TRAF2, NCK-interacting protein kinase and PDGFRA." (PMID 38215077, 2024). "Histamine, primarily originating from mast cells but released by several kinds of cancer cells, engages the H1R receptor, initiating actomyosin contractions through the RhoA-ROCK signaling pathway." (PMID 38331871, 2024). "Previous reports have shown that EGFR activation mediates actin dynamics via RhoA signaling in various cancers." (PMID 39742082, 2024). "Rgnef, (aka ARHGEF28 and p190RhoGEF), impacts cancer progression by regulating RhoA activity, an essential feature of focal adhesion dynamics and cell motility." (PMID 39493347, 2024). "Collectively, we demonstrate that the phosphorylation of RhoGDI1 by PLK1 promotes cancer cell migration and invasion through RhoA activation." (PMID 38355643, 2024). "In cancer cells, Rac1 activity is suppressed at the cell equator during metaphase and anaphase to promote RhoA-dependent restriction of actomyosin contractility to a narrow zone for efficient membrane ingression in early cytokinesis." (PMID 38324689, 2024). "explored that ras homolog family member A (RhoA) knockdown prevented the release of EVs from cancer cells." (PMID 39611045, 2024). "IL-1β, commonly found in diverse types of cancer, activates RhoA signaling pathways when it binds to IL-1R, which then results in the phosphorylation of VE-cadherin." (PMID 38331871, 2024). "An array of cancers harboring oncogenic alterations of PIK3CA, KRAS, PTEN, EGFR, and RHOA have been reported to be associated with activated PI3K/AKT-mTOR signaling." (PMID 39164472, 2024). "In the current study, we identified PLK1 as a novel kinase of RhoGDI1 and provided new mechanistic insight into the regulation by PLK1 of cancer cell migration and invasion via RhoA activation." (PMID 38355643, 2024). "This study indicates that NEK2 promotes the metastatic behaviors of cancer cells by activating RhoA and Rac1 by phosphorylating RhoGDI1." (PMID 39768163, 2024). "For instance, 14-3-3 binds directly to RhoGDI1 phosphorylated at Ser174, releasing RhoA, Rac1, and Cdc42, promoting Rho GTPases activation and resulting in increased cancer cell invasion and metastasis." (PMID 39768163, 2024). "Overall, a plethora of signalling cascades have been reported to be activated downstream of ASIC activation in different carcinomas – increase in ROS, activation of RhoA, NFAT, PI3K, or AKT—all due to an increase in [Ca2+]i triggered by ASICs." (PMID 38175291, 2024). "It would then be interesting to study the Rho protein pathway within the different lines to further understand how NDR2 promotes the YAP activation in hypoxia, hypoxia being also involved in cancer cell migration via the RhoA pathway." (PMID 38092743, 2023).
cancer (continued). "Through modulation of RhoA-dependent integrin clustering and actin stress fiber formation, propofol can effectively inhibit the invasion of human cancer cells in vitro at clinically relevant concentrations." (PMID 36762306, 2023). "Based on the reported researches, ARHGEF12 binds to RhoA to shape a functional complex, thereby enhancing cancer cell migration and invasion." (PMID 37731740, 2023). "Tumour suppressor functions of RhoA also suggest a context and cell-type specific function for Rho GTPases in cancer." (PMID 36854376, 2023). "Since hAM preparations strongly reduced the migration of cancer urothelial cells, we further investigated their effect on the expression of key components required for efficient cell migration, such as cortactin, RhoA, RhoC, Cdc42 and Rac1." (PMID 37932474, 2023). "LPS, a well-known proinflammatory agent, was shown to promote the progression of cancer cells by simultaneously activating NF-κB and inducing the phosphorylation of Tyr42 in RhoA, thus facilitating the interaction between these two proteins." (PMID 38136210, 2023). "It has been shown that GEF-H1 activates RhoA to promote or inhibit cancer metastasis in a cellular-context-dependent manner." (PMID 37193711, 2023). "Propofol can prevent the invasion of human cancer cells in vitro at therapeutically relevant dosages via modulating RhoA-dependent clumping of integrins and synthesis of actin stress fibers." (PMID 36762306, 2023). "We and others previously showed that SLIT2-ROBO1 signaling robustly activates RhoA, which in turn can activate Rho-associated protein kinases (ROCK), in several cell types, including macrophages and cancer cells." (PMID 37773612, 2023). "Notably, we also found that several cancer-related mutation sites in RhoA, such as A3, R5, and E5453–55, are located at the interface with the TRPV4 ARD, providing evidence for an interplay between TRPV4 and RhoA in cancer, although these RhoA mutations may also impact effector binding more broadly." (PMID 37353484, 2023). "They demonstrated that cancer cells activate RhoA-myosin II and stiffen in response to shear stress." (PMID 37490147, 2023). "Arap3, a dual GTPase-activating protein (GAP) for the small GTPases Arf6 and RhoA, plays key roles in regulating a wide range of biological processes, including cancer cell invasion and metastasis." (PMID 36674645, 2023). "In line with our previous findings, we observed that β5 clustering in FAs is favored in cells that express constitutively active RhoA and that the localization of β5 in different cancer cells is positively correlated with the amount of cellular tension." (PMID 35532004, 2022). "Circ-133 can be delivered into relatively normoxic cells and targeted to GEF-H1/RhoA by sponging miR-133a, which serves to decrease the expression of E-cadherin on the surface to enhance the migration capacity of cancer cells." (PMID 36238299, 2022). "Cell invasion associated with cancer progression requires EMT, and the activation of RHOA via TGFβ1 signaling induces GC cell migration via EMT." (PMID 35804944, 2022). "The phosphorylation of RhoA can promote the cancer process and cancer cell invasion and migration in NPC." (PMID 35075114, 2022). "Numerous miRNAs regulate the expression of RhoA, including miR-155, miR-31, miR-122, and miR-146a, but these have mainly been studied in relation to cancers." (PMID 35563826, 2022). "RhoA inactivation is directly involved in the morphological changes of cancer cells, mainly mediated by cytoskeleton reorganization." (PMID 35758029, 2022). "The higher expression or activation of RhoA has been observed in various cancer types such as breast, gastric, head and neck squamous cell carcinoma, and hepatocellular carcinoma." (PMID 35273919, 2022).
cancer (continued). "We also tested the effects of RhoA in the H1975 cells, which express EGFR L858R and T790M mutations and form metastasis in mice even when osimertinib treatment is started 2 days after cancer cell injection (black and gray curves)." (PMID 36509758, 2022). "In cancer cells, the classical NF‐κB pathway is activated by mechanical cues and RhoA‐ROCK‐myosin II signaling." (PMID 34957688, 2022). "Accordingly, the RhoA/ROCK1-2 pathway has been suggested as a possible therapeutic target in cancer." (PMID 35604542, 2022). "Conversely, S1P regulates and inhibits the movement of cancer cells via a S1P receptor 2-dependent activation of RhoA." (PMID 35619906, 2022). "The abnormal activation of ROCK1 kinase causes several disorders, whereas numerous studies have also shown that RhoA is expressed highly in various cancers, including colon, lung, ovarian, gastric, and liver malignancies." (PMID 36500403, 2022). "Previous studies have shown that RhoA/JNK plays crucial roles during cancer metastasis by decreasing cell–cell contact and increasing cell migration and invasion." (PMID 35725908, 2022). "The top 10 frequently affected cancer-associated genes are HIRA (OG), CSMD1 (TS), CDH13 (TS), PRRX1 (OG), FHIT (TS), MGAM (OG), TBL1XR1 (OG), RHOA (OG), FGF14 (TS), and CNTNAP2 (TS)." (PMID 35013466, 2022). "At the molecular level, upregulation of miR-509-3p was found to potentiate the expression of RhoA with a concurrent decrease in the levels of epithelial marker E-Cadherin – genes critical to the EMT process of cancer progression." (PMID 35361144, 2022). "In malignant tumors of the hematopoietic and lymphatic system, GNA13 and RhoA mutations are present in B-cell lymphomas, mainly in DLBCL and Burkitt’s lymphoma." (PMID 35237598, 2022). "The EGFR/RhoA/PKCα/ERK signaling pathway has been previously reported to modulate cancer progression and metastasis through EMT." (PMID 35804959, 2022). "Taken together, eIF3a accelerates the acquisition of the migratory phenotype of cancer cells by activating Cdc42 and RhoA expression at the translational level." (PMID 35300416, 2022). "A substantial number of cancer-associated point mutations in predominantly RAC1, RHOA, and CDC42 have been found and characterized." (PMID 35454871, 2022). "Another member of the Rho family, ras homologue family member A (RhoA), is hyperactivated in several types of human cancer." (PMID 35300416, 2022). "To further clarify the role of ANKFN1 in HCC migration and invasion in vitro, we postulated that ANKFN1 promotes cancer migration and invasion by regulating the RhoA/JNK signaling pathway." (PMID 35725908, 2022). "Meanwhile, the activity of Smurf1 in mediating RhoA degradation is critical for cancer cell invasive activity." (PMID 35654587, 2022). "RhoA is a member of the Ras superfamily, which regulates cell migration and invasion of cancer cells." (PMID 35571115, 2022). "In the new landscape of cancer genomics, activating point mutations in members of the RHO GTPases have been identified, in particular in RAC1, RHOA, and CDC42, which has suggested that RHO GTPases can indeed serve as oncogenes in certain cancer types." (PMID 35454871, 2022). "RhoA is a family of GTPases, and several studies have revealed high RhoA expression in various cancers and described the active role of RhoA in different pathways that are implicated in tumorigenesis." (PMID 35941537, 2022). "RhoA was primarily found in the cytoplasm, with a substantially higher expression rate in carcinomas (62.3%, 81/130) than in paracancerous tissues (18.5%, 24/130)." (PMID 36207695, 2022). "Here we show that RKIP inhibits cancer cell invasion and metastasis by stimulating RhoA anti-tumorigenic functions." (PMID 34465801, 2021). "RhoA has been originally studied in cancer cells and is well-studied with regard to its role in stimulating cell cycle progression and maintenance of actin-dynamics." (PMID 33906663, 2021).
cancer (continued). "It has been proven that RHOA up-regulation is tightly connected with cancer progression, treatments and prognosis." (PMID 33639650, 2021). "Previous studies of the function of KAI1 mostly focused on activation of T cells and inhibition of metastasis and migration through suppression of Rac1/RhoA activity in the cancer cells." (PMID 34530889, 2021). "HIFs activate transcription of the Rho family member RHOA and Rho kinase 1 (ROCK1) genes, leading to cytoskeletal changes, focal adhesion formation and actomyosin contractions that underlie the invasive cancer cell phenotype." (PMID 34415238, 2021). "MYC-orchestrated RhoA transcription has been shown to be pivotal in cell invasion and cancer metastasis, and MYC-regulated genes are one of the major targets held responsible for the antiproliferative effects of BET inhibitors in DLBCL." (PMID 34638508, 2021). "Following the progression towards cancer, our model shows an imbalance between the two opponents ras homolog family member A (RHOA) and ras-related botulinum toxin substrate 1 (RAC1) in favor of RAC1." (PMID 33578795, 2021). "Cancer-associated fibroblast exosomes (CAF-Des) with a heavy load of ADAM10 enhance the motility of cancer cells through GTPase-mediated RhoA and NOTCH signaling." (PMID 34821724, 2021). "To address this possibility, we sub-optimally knockdown the expression of RhoA in RKIP ectopically expressed 4T1 for orthotopic cancer cells transplantation assay." (PMID 34465801, 2021). "RhoA activation, similar to the activation of other Rho family GTPases, plays an important role in enhancing cancer cell motility." (PMID 34650915, 2021). "It is included in the oxytocin signaling pathway and hence, RhoA/Rho kinase pathways are also activated, contributing to the invasion of cancer cells." (PMID 33800915, 2021). "RHOA overexpression was observed frequently in many metastatic cancer cell types and cancer tissues, and was first found to be upregulated in human colorectal tissue in 1999." (PMID 33406731, 2021). "The migratory machinery of cancer cells is depended on interactions between specific cell cytoskeletal proteins coordinated by small GTPases, such as the Rho family of proteins (RHOA, CDC42 and RAC-1." (PMID 34321041, 2021). "In in vitro experiments Rhosin-induced inhibition of RhoA lead to decrease proliferation of different cancer cells lines." (PMID 33906663, 2021). "NEK9-medidated ARHGEF2 phosphorylation contributes to increased cell movement by inducing direct transformation of inactive RhoA to the active state to enable local invasiveness and distant metastasis of cancer cells." (PMID 33500736, 2021). "The activation of RhoA, Rac1/2/3 and cdc42 small GTPases exerts an important molecular switching effect on cancer cell proliferation, migration, and invasion." (PMID 34345201, 2021). "RhoA is a protein of multiple cellular regulatory functions that can either enhance or stymie cancer progression and metastasis." (PMID 34465801, 2021). "RHOA is a small GTPase protein known to regulate malignant transformation and motility of cancer cells." (PMID 33568634, 2021). "ROCK2, a member of ROCK family and the downstream effector of RhoA, is involved in the regulation of various cancer cell contraction, migration, invasion and survival." (PMID 33407478, 2021). "Mis-localized cytoplasmic p27, seen in cancers, selectively binds RhoA, inhibiting the activation of RhoA by the GEFs, and this promotes cell migration." (PMID 33546351, 2021). "For instance, it has been reported that RHOA is downregulated by miR-340-5p and mir-200 to inhibit cancer progression." (PMID 34771549, 2021). "The Ras homolog gene family member A (RhoA) is the founding member of Rho GTPase superfamily originally studied in cancer cells where it was found to stimulate cell cycle progression and migration." (PMID 33906663, 2021).